EGFR (epidermal growth factor receptor)
Diseases named in the same sentence as EGFR in open-access papers (continued):
Sharing a sentence is not in itself a finding about the gene and the disease.
glioma (continued). "Reports have pointed out that TERT was able to enhance stemness of glioma cells by modulation of epidermal growth factor receptor (EGFR) expression." (PMID 33869033, 2021). "In this context, a series of pentacyclic triterpene analogues were subjected to in vitro and in silico assays, which were conducted to assess their potency as EGFR-targeted anti-glioma agents." (PMID 34681605, 2021). "As before, targeting EGFR remained highly attractive due to the high frequency of abnormalities in this pathway in high grade gliomas." (PMID 34926242, 2021). "It has been found that, overexpression of EGFR and mutation/deletion of PTEN is one of the main genetic changes identified in gliomas." (PMID 33790740, 2021). "Over the years, these models have led to a better understanding of the role of EGFR, PDGFRs, and other RTKs in gliomagenesis as well as glioma progression, and have been crucial for testing new, potentially active therapeutic agents." (PMID 34830952, 2021). "When EGFR and Annexin A2 proteins are simultaneously highly expressed in human glioma cells, the role of the MAPK signaling pathway is significantly enhanced, promoting the aggressive growth of human glioma cells." (PMID 34376212, 2021). "In fact, LRIG3 acts as a tumor suppressor in GBM, where it modulates proliferation, migration, and invasion of glioma cells by targeting the EGFR and MET signaling pathways." (PMID 33718179, 2021). "It is known that epidermal growth factor receptor (EGFR) amplification is a characteristic of the classical subtype of glioma." (PMID 33435537, 2021). "GBM is characterized by abnormal activation of receptor tyrosine kinase signaling pathways, and constitutively activated STAT3 is frequently coexpressed with epidermal growth factor receptor (EGFR) in high-grade gliomas." (PMID 33980886, 2021). "Several studies have suggested a correlation between EGFR alterations and glioma tumor growth, survival, invasion, and angiogenesis." (PMID 35601813, 2021). "Taken together, our data suggests that TRAF2–DYRK1A–SPRY2 interaction is important for regulating EGFR stability in glioma cells." (PMID 34117217, 2021). "GBM tumor subtyping is based on gene amplification of actionable key glioma drivers (50% EGFR amplification in classical or 10–15% PDGFRA amplification in proneural subtypes)." (PMID 34830952, 2021). "In another study, epidermal growth factor receptor (EGFR) gene silencing was performed in human gli36-Luc glioma cells." (PMID 35047931, 2021). "Owing to the development of molecular oncology, novel targeted therapies for the treatment of glioma have been developed, among which the epidermal growth factor receptor (EGFR) is an important target." (PMID 34635007, 2021). "Gliomas require a complex signaling network that dictates the tumor sensitivity of EGFR-targeted therapies." (PMID 33435537, 2021). "The extended period of treatment and disease stability of our EGFR vIII patients demonstrates the potential activity of osimertinib in select patients with EGFR vIII altered gliomas." (PMID 35601813, 2021). "The application of EGFR-targeted therapy for glioma treatment has been less successful than expected." (PMID 33435537, 2021). "According to the information from the datasets in Oncomine, in Sun’s datasets, the mRNA levels of EGFR were 9.390, 5.740, and 8.211 times higher in glioma tissues with different histological types than in normal tissues." (PMID 33892666, 2021). "A radiomics algorithm formed by texture features extracted from T2WI shows a good prediction of EGFR level in lower-grade gliomas." (PMID 34422648, 2021). "Another study has tested the effects on three related human glioma cell lines treated by the new epidermal growth factor receptor (EGFR) tyrosine kinase Tyrphostin-AG-1478, and found that AG-1478 was the relatively specific inhibitor of truncated EGFR." (PMID 33407085, 2021).
glioma (continued). "To understand the role of autophagy in the pathogenesis of glial tumors in vivo, we used an established Drosophila melanogaster model of glioma based on overexpression in larval glial cells of an active human EGFR and of the PI3K homolog Pi3K92E/Dp110." (PMID 33978540, 2021). "We found that elevated NEK8 expression in glioma is associated with various clinical and pathological parameters (WHO grade, histological type, IDH, EGFR, PIK3CA status and primary therapy outcome) and survival time." (PMID 34374193, 2021). "In silico pharmacokinetic evaluation indicates that compound 10 is a promising bioavailable anti-glioma drug candidate targeting EGFR for further studies." (PMID 34681605, 2021). "The amplification of the EGFR gene affects the development and progression of gliomas, conferring more aggressive properties, and can be used as a therapeutic target." (PMID 33762015, 2021). "In continuation of our mechanistic research, the inhibitory effects of compound 10 on EGFR were analyzed due to the correlation between diminished EGFR signaling with increased anti-glioma activity." (PMID 34681605, 2021). "In vitro studies reveal that compound 10 exerts anti-glioma action through the induction of apoptosis and the inhibition of EGFR." (PMID 34681605, 2021). "Due to the important role of the EGFR pathway in glioma, the interest in therapeutically targeting EGFR increased rapidly over the past few decades." (PMID 34209513, 2021). "Robust expression of oncogenic and truncated forms of epidermal growth factor receptor (EGFR) vIII in glioma cells augmented exosomal secretion and transfer of oncogenic activity to other normal cells." (PMID 33477340, 2021). "EJ28Luc (bladder) and LN18 (glioma) cancer cells, both overexpressing EGFR, were incubated for 3 h with the radioimmunoconjugate." (PMID 33737524, 2021). "Previous clinical studies on anti-EGFR antibody in glioma have found that antibody-mediated therapy has a potential application prospect." (PMID 34630121, 2021). "Intriguingly, due to the functional impact of EGFR alterations on tumor aggressiveness, lower- grade gliomas harboring EGFR amplification are considered “GBM-like tumors” due their aggressive phenotypic behavior." (PMID 34178638, 2021). "In other words, the expression of either EGFR or PDGFRs, drivers of glioma progression, is rarely included when assessing the efficacy of a drug." (PMID 34830952, 2021). "We also found significant enrichments of EGFR-mutated IDHwt (FDR = 7.03E-10) and IDH1-mutated IDHmut-codel gliomas (FDR = 0.020) in later-onset cases." (PMID 34788626, 2021). "The incidence of malignant factor, EGFR amplification and PTEN mutation, was significantly higher in glioma samples with higher expression levels of UBE2S compared with those with low expression levels." (PMID 34123793, 2021). "The EGFR gene’s mRNA expression showed the strongest correlation with its protein expression in all three pathohistological types of gliomas." (PMID 34209611, 2021). "Due to the scarcity of studies describing the impact of osimertinib on gliomas in humans, we report our clinical experience of using osimertinib in patients with gliomas containing EGFR alterations." (PMID 35601813, 2021). "P38 was shown to promote EGFR endocytosis, and its pharmacological inhibition leads to sustained EGFR expression in glioma stem cells." (PMID 34831480, 2021). "On the other hand, EGFR was barely expressed in the normal brain tissues and low-grade gliomas, but was overexpressed in the grade III–IV gliomas." (PMID 34461927, 2021). "Results showed that compared with the copy numbers in normal brain tissues and grade I gliomas, the copy numbers of EGFR were significantly elevated in GBM, while the copy numbers of LANCL2 had no obvious changes." (PMID 34461927, 2021). "For these experiments, the nanocells were loaded with miR-34a or control miRNA and with a bispecific antibody against EGFR on glioma tumor cells." (PMID 33765907, 2021).
glioma (continued). "Using flow cytometry analysis, they demonstrated that EGFR expression in serum EVs can accurately distinguish high-grade glioma patients from low-grade glioma patients." (PMID 34638714, 2021). "Based on in vitro and in silico data, compound 10 stands out as a potential orally bioavailable EGFR-targeted anti-glioma agent endowed with the ability to cross the blood–brain barrier (BBB)." (PMID 34681605, 2021). "Our core target EGFR had significant positive correlation results in Thymoma, Kidney Chromophobe, Diffuse Large B-Cell Lymphoma, Brain Lower Grade Glioma, and Skin Cutaneous Melanoma." (PMID 33968733, 2021). "MVP enhances glioma aggressiveness through the epidermal growth factor receptor (EGFR)/phosphatidylinositol 3-kinase (PI3K) signaling axis." (PMID 33875619, 2021). "The expression level of EGFR mRNA was notably positively correlated with the level of B cell infiltration in glioma tissue (r = 0.1671, p < 0.0001)." (PMID 33892666, 2021). "In total, two studies were found which investigated the relationship between MR radiomics and EGFR alterations in glioma, more precisely, between EGFR over-expression in LGG patients and EGFR mutation in GBM patients." (PMID 34208595, 2021). "For instance, Golgi phosphoprotein 3 (GOLPH3), a protein implicated in multiple cellular functions, was reported to promote glioma progression by inhibiting Rab5-dependent EGFR endocytosis." (PMID 34831480, 2021). "The oncogene lncRNA SNHG16, in contrast, functioned in the proliferation, aggression and migration of glioma cells through the miR373/EGFR/PI3K/AKT axis." (PMID 34178684, 2021). "Inversely, down-regulated TERT expression was coincided with declined expression of EGFR, basic fibroblast growth factor (bFGF) and glioma stem cell properties." (PMID 33869033, 2021). "Aberrant EGFR signaling leads to poor prognosis and low survival rates for GBM patients, poor responses to therapy, and earlier recurrence after treatment and therefore EGFR-targeted therapy has emerged as a promising approach for the management of gliomas." (PMID 34681605, 2021). "Most mouse models of glioma are generated by altering key signaling pathways disrupted in human gliomas, including Ras, EGFR, Akt, Rb, Pten, Nf1 and platelet-derived growth factor (PDGF)." (PMID 33869004, 2021). "Overexpression of Gn-T III in a human glioma cell line caused reduced EGF binding and EGFR phosphorylation, thus preventing EGFR activation." (PMID 34069424, 2021). "FEGFS can effectively identify the corresponding cell types from the glioma data and infer that EGFR is significantly expressed in the three tumors." (PMID 34917514, 2021). "EGFR overexpression can promote malignant proliferation of glioma cells, and several studies have focused on suppressing malignant proliferation by inhibiting its activity." (PMID 34422648, 2021). "The EGFR/mitogen activated protein kinase (MAPK) pathway is known to contribute to glioma progression." (PMID 34646821, 2021). "Suggestive associations were found between young adult THCA and gene fusions involving RET (FDR = 0.102) or NTRK3 (FDR = 0.102), as well as between later-onset gliomas and EGFR fusions (FDR = 0.102)." (PMID 34788626, 2021). "MiR-566 is overexpressed in human glioma cell and accelerates glioma cells proliferation and invasion as well as EGFR pathway activity." (PMID 37304650, 2021). "In the TCGA dataset, the expression of EGFR was 3.792- and 2.956-fold higher in glioma tissues with different histological types than in normal tissues." (PMID 33892666, 2021).
glioma (continued). "As in the present study, for IDH-wild-type grade II or III gliomas in TCGA database, TERTp status revealed almost all cases of “astrocytoma, grade 4” and the addition of EGFR status successfully identified all other cases of “astrocytoma, grade 4”." (PMID 34257410, 2021). "EGFR-induced gliomas also form in transgenic mice with a INK4a-ARF tumor suppressor locus disruption." (PMID 33806933, 2021). "We recently demonstrated in EGFR overexpressing glioma cells that extracellular S1P produced by SK1 is involved in the increased invasiveness through the activation of the EGFRvIII-ERK-SK1-S1P pathway via the S1P1 receptor." (PMID 34201962, 2021). "Encouraged by the scientific reports related to PTs exerting marked antitumor action through different mechanisms (e.g., EGFR signaling), in vitro and in silico assays were conducted to determine their potency as EGFR-targeted anti-glioma agents." (PMID 34681605, 2021). "EGFR endocytosis and membrane trafficking, which tightly regulate EGFR oncosignaling, are often dysregulated in glioma." (PMID 34831480, 2021). "The main factors responsible for the low efficacy include the heterogeneity of EGFR molecules and glioma tissues, complication of EGFR downstream signaling pathways, and difficulty of EGFR antagonists to pass through the BBB." (PMID 34635007, 2021). "Analysis showed that UBE2S expression was positively associated with PTEN-mutation and EGFR amplification and negatively associated to IDH1-mutation and co-deletion of 1p19q in whole grade glioma." (PMID 34123793, 2021). "At the molecular level, O-6-methylguanine- DNA methyltransferase promoter methylation, EGFR alterations, IDHI or IDH2 mutation, and 1p19q codeletion are tested to diagnose gliomas." (PMID 34552618, 2021). "Fusion-subtype pairs identified enrichment of EGFR-fusion IDHwt gliomas in the later-onset cohort (STAR Methods)." (PMID 34788626, 2021). "We have previously shown that microglia stimulate invasion of murine and human glioma cell lines and this is dependent on CSF-1R and EGFR signaling in a putative paracrine interaction." (PMID 34843542, 2021). "Our results showed that constructed multiparametric model from MRI radiomics features can identify IDH1, ATRX, MGMT, and EGFR in preoperative MRI scans of patients with glioma." (PMID 34056604, 2021). "EGLN3 elaborates the growth-suppressive function by suppression of EGFR signaling, which independent to HIF1α and NF-κB in gliomas." (PMID 34112167, 2021). "EGFR-KDD is most prevalent in glioma and NSCLC, while ERBB2-KDD is most prevalent in breast and gynecological cancers (GYN)." (PMID 33654076, 2021). "Quantitative proteomics was adopted to characterize 200 paired EGFR-positive and EGFR-negative glioma tissues of all pathological types, and EGF-like domain multiple 7 (EGFL7) was identified as a potential diagnostic biomarker and therapeutic target." (PMID 34095463, 2021). "EGFR is a prognostic marker that has to be combined with other molecular markers in order to identify different glioma subtypes." (PMID 33946969, 2021). "Within the Molecular Tumor Board, we initially identified 16 patients with advanced high-grade glioma and focal EGFR amplification based on molecular profile evaluations." (PMID 32705082, 2020). "We chose the three genes most significantly enriched in the high-EGFR gliomas: GOSR1, TMEM167A, and STX17." (PMID 31947645, 2020). "We previously showed that inhibition of EGFR and mTORC1 protects glioma cells from hypoxia-induced cell death." (PMID 32756332, 2020). "We present a single-center cohort of 9 advanced EGFR-amplified high-grade gliomas treated with the antibody-drug conjugate (ADC), Depatuxizumab Mafodotin (Depatux-M, ABT-414)." (PMID 32705082, 2020).
glioma (continued). "Taken together, our study provides clinical and mechanistic evidence demonstrating that SH3KBP1 high expression is essential for EGFR driven tumorigenesis in glioma." (PMID 33643898, 2020). "Here we demonstrate that glioma organoids and PDOXs accurately maintain distinct genetic backgrounds of parental tumors, including gene amplifications of EGFR, PDGFRA, MET, MDM2/4, and CDK4/6, which are difficult to derive and preserve in vitro." (PMID 33009951, 2020). "NEAT1 acts as an oncogene in a series of human cancers including gliomas, where it is regulated by the Epidermal Growth Factor Receptor (EGFR) pathways, and contributes to tumor growth and invasion." (PMID 32443824, 2020). "Recent investigations have started to explore EGFR overexpression mechanisms in gliomas outside of genetic alterations, including the role of epigenetics." (PMID 33321953, 2020). "In this study, QDs were conjugated to a deoxyribonucleic acid oligonucleotide aptamer designed to bind to EGFR variant III (EGFRvIII), which is known to be expressed specifically on glioma cells." (PMID 32582530, 2020). "Mutations in the Telomerase Reverse Transcriptase promoter (TERTp) have been found in 80% of gliomas, mostly in tumors with EGFR alterations." (PMID 32570988, 2020). "Results show significant correlation between AEBP1 upregulation and increased EGFR expression in primary glioma." (PMID 32938364, 2020). "We explore EGFR-mutant glioma evolution in conditional mutant mice by whole-exome sequencing, transposon mutagenesis forward genetic screening, and transcriptomics." (PMID 32727536, 2020). "In contrast to T98G cells, U87 cells overexpress tissue transglutaminase (tTG), a GTP-binding protein/acyltransferase that is upregulated in many gliomas enhancing the signaling activity and lifespan of EGFR." (PMID 33238647, 2020). "Therapeutic potential when combining with other drugs used to treat gliomas has been suggested, whilst we additionally and concordantly identify EGFR amplification as a biomarker." (PMID 33274713, 2020). "Resistance to EGFR-targeted therapies in high-grade gliomas has been established to occur via both EGFR-dependent and EGFR-independent mechanisms." (PMID 35582224, 2020). "EGFR upregulation in the presence of VEGF has been well studied in glial tumors, where EMT transition can be initiated for oncogenesis." (PMID 32485834, 2020). "A recent study showed that ANGPTL4 induces temozolomide resistance in U87 and Pt#3 GB cell lines by promoting glioma stem-like cells enrichment via the EGFR/AKT/4E-BP1 signaling pathway." (PMID 32867190, 2020). "In present study, we found that expression of miR-450a-5p was significantly lower, while the expression of EGFR was higher in the glioma tissue samples especially in metastatic glioma samples." (PMID 32820249, 2020). "The evaluation of EV EGFR levels in glioma patients was 86.96% sensitive and 83.7% specific in identifying patients with glioma." (PMID 33143170, 2020). "Overall, our results highlight the relevance of the endomembrane system regulation by TMEM167A in EGFR-dependent gliomas, because it controls a key step in the development of aggressive glioma, where EGFR signaling and autophagy maintenance converge." (PMID 31947645, 2020). "In gliomas with high PDIA3 expression, somatic mutations showed the correlation with loss of PTEN and amplification of EGFR; meanwhile, in PDIA3 low gliomas, mutations in isocitrate dehydrogenase (IDH) took 80%." (PMID 32687065, 2020).